OR3A1 (olfactory receptor family 3 subfamily A member 1)
Description:
Odorant receptor.
Synonyms: OR17-40; OLFRA03; OR40; OR17-82
Tractability: Antibody: its Gene Ontology location is reachable by antibodies, with high confidence; UniProt places it where antibodies can reach, with medium confidence; UniProt predicts a signal peptide or a membrane-spanning region.
Gene: Protein-coding gene on chromosome 17 (3,291,017 to 3,298,360, reverse strand). Ensembl gene ENSG00000180090.
Subcellular location: Cell membrane
Pathways (Reactome):
Sensory Perception: Expression and translocation of olfactory receptors; Olfactory Signaling Pathway
Gene Ontology:
Molecular function: olfactory receptor activity; G protein-coupled receptor activity
Biological process: signal transduction; detection of chemical stimulus involved in sensory perception of smell; G protein-coupled receptor signaling pathway
Cellular component: plasma membrane; membrane
Genetic constraint (gnomAD): Missense variants: 393 observed, 399.3 expected, observed/expected ratio (o/e) 0.98, 90% interval 0.9 to 1.07. Synonymous variants: 143 observed, 161.88 expected, observed/expected ratio (o/e) 0.88, 90% interval 0.77 to 1.01.
Homologues: Orthologues: chimpanzee OR3A1 (98% identical), macaque OR3A1 (96% identical), rabbit OR3A1 (88% identical), dog OR3A1 (86% identical), mouse Or3a1 (85% identical), rat Or3a1 (85% identical), rat Or3a1e (84% identical), mouse Or3a1c (83% identical), mouse Or3a1b (81% identical), rat Or3a1f (80% identical), pig OR3A1 (80% identical). Paralogues in human: OR3A2 (81% identical), OR3A3 (77% identical), OR1K1 (45% identical), OR1F1 (45% identical), OR7D4 (45% identical), OR1J4 (44% identical), OR7A17 (44% identical), OR1S1 (44% identical), OR1J1 (43% identical), OR1N1 (43% identical), OR1N2 (43% identical), OR7A10 (43% identical), and 116 more.